ALDH1A3 (aldehyde dehydrogenase 1 family member A3)
Diseases named in the same sentence as ALDH1A3 in open-access papers (continued):
Sharing a sentence is not in itself a finding about the gene and the disease.
glioma (continued). "Evidence supports that ALDH1A1’s expression is higher in high-grade gliomas than in low-grade gliomas, whereas ALDH1A3 is expressed in most GBM cases but not in normal tissues and low-grade gliomas." (PMID 37686694, 2023). "We provide evidence that human GSCs express uniformly ALDH1A3 but not the ALDH1A1 isoform, whereas non-stem glioma cells express both isoforms at comparable levels." (PMID 35052687, 2021). "Notably, ALDH1A3, rather than ALDH1A1, is predominantly expressed in GSCs, whereas non-stem glioma cells comparably express both isoforms." (PMID 39519068, 2024).
melanoma (30 papers, 2013 to 2025). A malignant, usually aggressive tumor composed of atypical, neoplastic melanocytes. "In mouse melanoma models, we find Aldh1a3 expression is tightly associated with dedifferentiated, NC, and stem cell states, which have been reported to fuel cancer growth in a cellular hierarchy." (PMID 38963759, 2024). "The same authors also evidenced that ALDH1A inhibition and ALDH1A3 depletion both caused apoptosis induction in melanoma cells." (PMID 34943045, 2021). "Downregulation of ALDH1A3, which encodes for the most abundant aldehyde dehydrogenase isoform present in melanoma, suggests a weakened response to detoxification." (PMID 28785021, 2017). "Accordingly, a recent study demonstrated potentiation of transcriptional heterogeneity in melanoma by ALDH1A3-acetaldehyde metabolism." (PMID 40781158, 2025). "Together, these results support a combination therapeutic strategy using BRAF inhibitors to target the tumor bulk and NAZ to eradicate the ALDH1A3-melanoma stem cell pool in the residual disease." (PMID 38963759, 2024). "Here, we uncover that nuclear ALDH1A3, functioning as a master coordinator of metabolic and transcriptional cell states, fosters stem-like gene expression programs in melanoma by using pyruvate-derived acetaldehyde as an acetyl donor for histones." (PMID 38963759, 2024). "In melanoma patients with BRAF mutations, high ALDH1A3 expression correlates with favorable responses to BRAF/MEK inhibitor therapy." (PMID 39796106, 2024). "With this new resource, we employed MPD001 and MPD002 cells from patients with BRAFV600-mutant melanoma, with relatively low and very high levels of ALDH1A3, respectively." (PMID 38963759, 2024). "In this study, we discover that the pan-cancer stem cell marker ALDH1A3 is a central regulator of both metabolic and stem cell transcriptional states in melanoma." (PMID 38963759, 2024). "In agreement with our findings in human melanoma, we found that aldh1a3 was the most enriched ALDH family isoform in the ALDHHigh cells, together with high tfap2b, sox2, and sox10, while melanoma cells with ALDHLow activity expressed irf1b." (PMID 38963759, 2024). "ALDH1A1 is predominantly expressed in human melanoma tumor samples, whereas ALDH1A3 is predominantly expressed in human melanoma cell lines." (PMID 36694633, 2023). "Further, consistent with ALDH1A3′s role in metastasis, increased incidence of ALDH1A3 gene amplification occurred in datasets of metastatic prostate, breast, and melanoma." (PMID 36672441, 2023). "ALDH1A3 knockdown melanoma cell lines resulted in decreased cell proliferation and increased apoptosis." (PMID 36672441, 2023). "Lou and colleagues reported that both members of the ALDH1 family are increased in human melanoma cell lines, whereas more recently, Pérez-Alea and colleagues indicated ALDH1A3 as the enzyme majorly expressed in cultured melanoma cells." (PMID 34943045, 2021). "In melanoma cells, ALDH1A3 is upregulated through epigenetic mechanisms, as compared to normal melanocytes." (PMID 30733805, 2019). "As expected, ALDHhigh melanoma cells express significantly higher levels of ALDH1A3, SOX2 and CD271 than ALDHlow cells by real time PCR, western blotting (SOX2/ALDH1A1) and FACS analysis (CD271)." (PMID 28036292, 2017). "Of note, several of the other genes with decreased expression upon knockdown of Tfap2a have been reported in the literature as activated (Aldh1a3, Igf2bp1, Ephb2, Pbk) or downregulated (Qpct, Wfdc1) in melanoma." (PMID 28249010, 2017). "The secretome of senescent melanoma cells induces a panel of 52 genes, involved in cell movement and cell/cell interaction, among which AXL and ALDH1A3 have been implicated in melanoma development." (PMID 24344100, 2013). "Interestingly, four genes known to be related to cancer cell stemness in malignant melanoma (ALDH1A3, BSG, NGFR, SOX2) were expressed at significantly high levels in CTCs with a high “platelet signature” (p = 0.0204, 0.0012, 0.0183, 0.0200, respectively)." (PMID 40003901, 2025).
melanoma (continued). "Thus, in five independent melanoma patient datasets, ALDH1A3 expression correlates with TFAP2-NCSC expression." (PMID 38963759, 2024). "ALDH1 (ALDH isozyme 1), specifically the isoforms ALDH1A1 and ALDH1A3, have been reported to be highly expressed and even overactivated in melanoma CSCs and to correlate with different biological properties of tumor-initiating cells, such as tumorigenesis and drug resistance." (PMID 39199632, 2024). "To investigate whether the improved outcomes are achieved via on-target effect of NAZ, we examined Aldh1a3 levels in NAZ-treated zebrafish melanomas in progressive, drug-resistant disease and found that Aldh1a3 clusters were absent." (PMID 38963759, 2024). "The ALDH1A3 metabolism-stem cell axis represents a potential therapeutic vulnerability in melanoma." (PMID 38963759, 2024). "However, ALDH1A3 mRNA expression was more than 200 times higher than ALDH1A1 in ALDEFLUOR+ subpopulations isolated from melanoma cell lines." (PMID 37686694, 2023). "ALDEFLUOR-positive melanoma CSCs were associated with chemoresistance, and ALDH1A (ALDH1A1 and ALDH1A3) silencing could attenuate cell proliferation and induce apoptosis in ALDEFLUOR-positive melanoma CSCs in vitro and suppress melanoma tumorigenesis in vivo." (PMID 36651035, 2023). "In melanoma cells, ALDH1A3 knockdown reduced tumor growth activity." (PMID 36672441, 2023). "In cellular models of lung cancer and melanoma, ALDH1A3 and PD-L1 expression are correlated." (PMID 36139578, 2022). "constructed a mutational subtype of melanoma based on the BRAF mutation patterns of 2 FAM-related genes, ALDH1A1 and ALDH1A3; however, this CM subtype accounts for ALDH1A3 expression as only a prognostic marker for BRAF/MEK inhibitor treatment response in BRAF-mutant metastatic melanoma patients." (PMID 36466837, 2022). "In particular, ALDH1A3 expression in melanoma cells was correlated with programmed death-ligand 1 (PD-L1) expression in non-small-cell lung carcinoma (NSCLC) tumor samples and led to the reduced proliferation of the peripheral blood mononuclear cells in the co-culture experiments." (PMID 34572930, 2021). "A recent study provided evidence that ALDH1A3 is epigenetically upregulated in nevi and melanoma." (PMID 29156643, 2017). "Moreover, ALDH1A3 is a marker of normal and malignant melanoma and a predictor of poor clinical outcome in this form of cancer." (PMID 28785021, 2017). "Indeed, in our two independent melanoma cell lines (control vs. ALDH1A3 KO), we detected higher levels of 13C2-labeled acetylated histone H3 proteins in cells with high ALDH1A3 activity, with the incorporation at H3K14ac and H3K23ac especially responsive to ALDH1A3 levels." (PMID 38963759, 2024). "However, immunohistochemistry and real-time quantitative reverse transcription-PCR (qRT-PCR) reveal that both ALDH1A1 and ALDH1A3 may be expressed in some melanomas." (PMID 35334544, 2022). "In contrast, TFAP2A, a related family member expressed in proliferative melanoma that shares near-identical binding motif with TFAP2B, was negatively correlated with ALDH1A3." (PMID 38963759, 2024). "ALDH1 has been found to be overexpressed in melanoma, with ALDH1A1 and ALDH1A3 being the two predominantly expressed isoforms." (PMID 39796106, 2024). "In silico TCGA analysis further revealed that melanoma tumors are enriched in ALDH1A1 and ALDH1A3 isoenzymes." (PMID 38201651, 2024). "Effects of ALDH1A3 connected to RA signaling were also demonstrated in melanoma, where gene expression signatures of ALDH+ melanoma cells include RA-driven target genes harboring RAREs." (PMID 36672441, 2023). "Human ALDH1A family comprises ALDH1A1, strongly expressed in xenografted melanoma, ALDH1A2, and ALDH1A3, strongly expressed in 1205L and A375 human melanoma cell lines and weakly expressed in xenografted melanoma." (PMID 35334544, 2022).
melanoma (continued). "Melanoma treatment with a novel irreversible isoform-specific ALDH1 inhibitor (DIMATE) or depletion of ALDH1A1 and/or ALDH1A3 results in the accumulation of toxic aldehydes, increased apoptosis, and decreased tumor growth in xenograft mouse models." (PMID 30733805, 2019). "A report examining melanoma CSCs described a number of genes that appear to be regulated by ALDH1A1 and/or ALDH1A3, including CDC42, a gene containing RAREs." (PMID 28423611, 2017). "More recently, Liao and coworkers developed a dual ALDH1A1+ALDH1A3 peptide–dendritic cell vaccine and found that it induces suppression of tumor growth by eliciting a peculiar T cell immunity that specifically targets ALDH+ melanoma cells." (PMID 39199632, 2024). "Altogether, the reason for the differences in ALDH1A1 and ALDH1A3 expression between primary melanomas and melanoma cell lines was not clear." (PMID 36651035, 2023). "In addition to these markers, melanoma CSCs show high ALDH activity, especially ALDH1A1 and ALDH1A3 isozymes." (PMID 35048028, 2021). "However, a recent study reported that both ALDH1A1 and ALDH1A3 correlated with favorable prognosis in metastatic BRAF wild-type and BRAF-mutant melanoma, respectively." (PMID 35048028, 2021). "GTex data revealed that ALDH1A3 expression is low or absent in nearly all normal tissues while it is enriched in discrete tumor types, including sarcoma, prostate cancer, pancreatic cancer, and melanoma." (PMID 41210994, 2025). "However, in melanoma cell lines (1205Lu, A375, WM239A, and HS294T), ALDEFLUOR activity may be mainly determined by ALDH1A3." (PMID 36651035, 2023). "Thus, genes controlling the turnover of vitamin D (CYP27B1, CYP24A1), vitamin A (ALDH1A3, AKR1B10), and cholesterol (CYP7B1), were up-regulated in psoriasis, whereas melanomas showed downregulation of genes regulating turnover of vitamin A (AKR1C3), and cholesterol (CYP39A1)." (PMID 26901218, 2016).
prostate carcinoma (24 papers, 2013 to 2025). A carcinoma that arises from epithelial cells of the prostate gland. "By analyzing data from PLCO database, the genes ALDH1A1 and ALDH1A3 were discovered related to prostate cancer risk." (PMID 33068330, 2020). "In this study, we discovered that rs4646653 in ALDH1A3 is related to an increased risk of prostate cancer." (PMID 33068330, 2020). "Aldehyde dehydrogenase 1A3 (ALDH1A3) has been implicated in the survival and proliferation of prostate cancer cells." (PMID 32375698, 2020). "A study reported that ALDH1A3 has a high expression in prostate cancer and is associated with progression‐free survival after prostatectomy." (PMID 33068330, 2020). "After adjusting for age and smoking status, we identified that the rs1330286 G allele in ALDH1A1 was associated with a decreased risk of prostate cancer, while the rs4646653 C allele in ALDH1A3 was strongly related to an increased risk of prostate cancer." (PMID 33068330, 2020). "In conclusion, our study demonstrated that the genetic variants in ALDH1A1 and ALDH1A3 may play an important role in the tumorigenesis of prostate cancer." (PMID 33068330, 2020). "However, rs1330286 in ALDH1A1 and rs4646653 in ALDH1A3 were the only two SNPs that are associated with risk of prostate cancer after FDR regulation (PFDR =0.036 and PFDR =0.036, respectively)." (PMID 33068330, 2020). "In conclusion, this study highlights the dual role of ALDH1A3 in prostate cancer cells, where it regulates both cellular senescence and the SASP." (PMID 40227735, 2025). "ALDH1A3 expression is also driven by androgens in prostate cancer, where androgen is the major mitogen for prostate cancer cells." (PMID 41210994, 2025). "In this study, we investigate the regulatory role of ALDH1A3 in radiotherapy for prostate cancer, especially its effects on cellular senescence and SASP." (PMID 40227735, 2025). "miR-187 targets ALDH1A3 in prostate cancer, and high miR-187 was correlated with favorable prognosis." (PMID 41210994, 2025). "In our study of ALDH1A3, we found that its high expression in prostate cancer cells is closely related to the cell’s radiation tolerance and disease prognosis." (PMID 40227735, 2025). "ALDH1A1 and ALDH1A3 are differentially expressed in metastatic tumors of patients with prostate cancer, and their expression levels oppositely correlate with clinical outcomes." (PMID 38169509, 2024). "Our study characterized a differential role of ALDH1A1 and ALDH1A3 genes as regulators of prostate cancer progression and metastatic growth." (PMID 38169509, 2024). "In prostate cancer, circular RNA circCYP241 indirectly upregulates ALDH1A3 by sponging microRNA miR-1301-3p, which targets ALDH1A3 transcripts." (PMID 36672441, 2023). "A previous study revealed that the expression of miR-187 was inversely correlated with ALDH1A3 expression in prostate cancer, with miR-187 being an upstream target of ALDH1A3." (PMID 36996494, 2023). "The siRNA-mediated knockdown of ALDH1A1 and ALDH1A3 expressions resulted in radiation therapy sensitization of prostate cancer cells." (PMID 34572930, 2021). "ALDH1A1 and ALDH1A3 were recognized as the main contributors to ALDEFLUOR enzymatic activity in prostate cancer cells." (PMID 34572930, 2021). "The immunohistochemical staining of primary prostate cancer tissues showed that ALDH1A3 expression is confined to luminal cells, while its RNA levels positively correlate with luminal markers and negatively correlate with basal markers." (PMID 34572930, 2021). "From the TCGA data of 333 primary prostate cancer, ALDH1A3 correlated with AR signaling pathway and corresponding luminal signature." (PMID 32375698, 2020). "Two SNPs were significantly associated with prostate cancer risk [rs1330286 in ALDH1A1: odds ratio (OR) = 0.88, 95% confidence interval (CI) = 0.83‐0.94, p = 2.45 × 10−4; rs4646653 in ALDH1A3: OR = 1.17, 95% CI =1.07‐1.27, p = 4.33 × 10−4]." (PMID 33068330, 2020).
prostate carcinoma (continued). "Crispr-Cas9 was used to knock out ALDH1A3 in prostate cancer luminal cells, and morphologic analysis as well as the Gene Set Enrichment Analysis (GSEA) were facilitated to discover the mechanisms of the resistance phenotype." (PMID 32375698, 2020). "From the metastatic prostate cancer samples database, the RNA sequencing data demonstrated that ALDH1A3 was down regulated in mCRPC group compared with the primary prostate cancer." (PMID 32375698, 2020). "Another group performed RNA sequencing for primary prostate cancer and mCRPC samples, ALDH1A3 also down regulated in mCRPC samples." (PMID 32375698, 2020). "We found, surprisingly, that ALDH1A3 was down regulated in metastatic castration resistant prostate cancer from previous sequencing data." (PMID 32375698, 2020). "It is also suggested that ALDH1A3 has a potential to be a predictor of survival in primary prostate cancer patients." (PMID 32375698, 2020). "ALDH1A3 responded to androgen dihydrotestosterone treatment and increased the oxidation of retinal to RA in human prostate cancer cells, and was supposed to be the predominant isoenzyme responsible for ALDH activity and tumorigenicity in most NSCLC." (PMID 27015121, 2016). "The results reveal the molecular mechanism of ALDH1A3 in prostate cancer cells." (PMID 40227735, 2025). "Furthermore, abnormal expression of ALDH1A3 promotes chemotherapy resistance in prostate cancer, via the PI3K/AKT/mTOR axis." (PMID 37551838, 2023). "Furthermore, it has been revealed that miR-187 drastically reduces ALDH1A3 expression and promotes the proliferation of prostate cancer cells." (PMID 36996494, 2023). "Moreover, the mRNA level of ALDH1A3 was significantly higher in prostate cancer tissues than in normal tissues in both TCGA datasets and GEO datasets (p = 1.63 × 10−12 and p = 4.33 × 10−2, respectively)." (PMID 33068330, 2020). "Our earlier work has demonstrated that ALDH1A3 highly expressed in human prostate, which had a strong correlation with primary prostate cancer luminal signature and could be a potential biomarker of AR signaling pathway." (PMID 32375698, 2020). "A number of the top genes identified in this study have previously been implicated in prostate cancer development and progression, Gleason grade, metastases and biochemical recurrence; including CANT1, FBP1, RRM2, POLE2, PDE4D, and ALDH1A3." (PMID 27980733, 2016). "Furthermore, we confirmed this hypothesis with experiments, supporting that ALDH1A3 null could facilitate prostate cancer cells in castrated condition via PI3K pathway, but could be rescued by PI3K pathway inhibitor." (PMID 32375698, 2020). "In prostate cancer, knockdown of both ALDH1A1 and ALDH1A3 enhanced radio sensitization, but only ALDH1A1 knockdown impaired DNA repair, suggesting a unique role for ALDH1A1 in maintaining cellular homeostasis upon radiation." (PMID 40076923, 2025). "These experiments suggest ALDH1A1 and ALDH1A3 as regulators of a transcriptional program driving CSC phenotype and radioresistance in prostate cancer cells." (PMID 38169509, 2024). "First, we conducted Spearman’s rho analysis on publicly available prostate cancer clinical samples to evaluate the potential correlation between ALDH1A3 and SASP genes; however, the results did not reveal a significant association." (PMID 40227735, 2025).